MED4 (mediator complex subunit 4)
Description:
Component of the Mediator complex, a coactivator involved in the regulated transcription of nearly all RNA polymerase II-dependent genes. Mediator functions as a bridge to convey information from gene-specific regulatory proteins to the basal RNA polymerase II transcription machinery. Mediator is recruited to promoters by direct interactions with regulatory proteins and serves as a scaffold for the assembly of a functional preinitiation complex with RNA polymerase II and the general transcription factors.
Synonyms: ARC36; DRIP36; VDRIP; HSPC126; TRAP36
Tractability: Small molecule: a structure with a bound ligand is known. PROTAC: ubiquitination databases record sites on it; its protein half-life has been measured.
Gene: Protein-coding gene on chromosome 13 (48,053,323 to 48,095,131, reverse strand). Ensembl gene ENSG00000136146.
Subcellular location: Nucleus
Subcellular location (Human Protein Atlas): Nucleoplasm
Pathways (Reactome):
Gene expression (Transcription): Generic Transcription Pathway; MLL4 and MLL3 complexes regulate expression of PPARG target genes in adipogenesis and hepatic steatosis
Developmental Biology: Transcriptional regulation of white adipocyte differentiation
Disease: RSV-host interactions
Metabolism: PPARA activates gene expression
Gene Ontology:
Molecular function: nuclear thyroid hormone receptor binding; protein binding; transcription coactivator activity; transcription coregulator activity; nuclear vitamin D receptor binding
Biological process: positive regulation of DNA-templated transcription; positive regulation of transcription initiation by RNA polymerase II; transcription by RNA polymerase II; positive regulation of transcription elongation by RNA polymerase II; regulation of transcription by RNA polymerase II; RNA polymerase II preinitiation complex assembly
Cellular component: core mediator complex; mediator complex; membrane; nucleoplasm; nucleus
Genetic constraint (gnomAD): Loss-of-function variants: 15 observed, 22.36 expected, observed/expected ratio (o/e) 0.67, 90% interval 0.45 to 1.03. The upper end of that interval is the gene's LOEUF score, 1.03, which puts it in group 4 of 6, group 1 being the genes least tolerant of losing a copy. Missense variants: 256 observed, 260.43 expected, observed/expected ratio (o/e) 0.98, 90% interval 0.89 to 1.09. Synonymous variants: 112 observed, 93.29 expected, observed/expected ratio (o/e) 1.2, 90% interval 1.03 to 1.4.
Homologues: Orthologues: chimpanzee MED4 (100% identical), macaque MED4 (99% identical), rabbit MED4 (97% identical), pig MED4 (97% identical), dog MED4 (96% identical), guinea pig MED4 (96% identical), mouse Med4 (94% identical), rat Med4 (92% identical), dog MED4 (80% identical), tropical clawed frog med4 (78% identical), zebrafish med4 (77% identical), Drosophila melanogaster MED4 (42% identical), and 1 more.
Diseases named in the same sentence as MED4 in open-access papers:
MED4 is named in the same sentence as 10 diseases in open-access papers, as found by Europe PMC text mining. Sharing a sentence is not in itself a finding about the gene and the disease. The quoted sentences say what the papers report.
retinoblastoma (3 papers, 2016 to 2022). A malignant tumor that originates in the nuclear layer of the retina. "It is established that the mean number of eyes with retinoblastoma in patients with large deletions is distinct depending on the loss of some adjacent genes, specifically the MED4 gene." (PMID 33807189, 2021). "As a result, when the RB1 c.1981C>T/p.Arg661Trp mutation is inherited from the mother, loss of the contralateral paternal allele in the tumor would switch off MED4 expression and prevent retinoblastoma development in the context of a low penetrance mutation." (PMID 26925970, 2016). "As a result, when the p.Arg661Trp mutation is inherited from the mother, loss of the contralateral paternal allele would dramatically decrease MED4 expression and prevent retinoblastoma development in the context of a low penetrance mutation." (PMID 26925970, 2016). "For instance, MED4, a synthetic lethal target in tumors, explains the low penetrance of retinoblastoma." (PMID 35960463, 2022). "We have recently shown that retinoblastoma RB1 -/- cells cannot survive in the absence of MED4, both in vitro and in orthotopic xenograft models in vivo, therefore identifying MED4 as a survival gene in retinoblastoma." (PMID 26925970, 2016). "Consequently, we considered a MED4-driven general mechanism to explain low penetrance retinoblastoma." (PMID 26925970, 2016).
breast carcinoma (1 paper, 2019). "MED1 and MED4 expression was generally slightly reduced with breast cancer progression, while MED14 expression was generally increased." (PMID 31695025, 2019). "In breast cancer, MED1 and MED4 expression was significantly reduced in tumors, while MED14 was increased." (PMID 31695025, 2019).
cervical cancer (1 paper, 2014). A primary or metastatic malignant neoplasm involving the cervix. "MED4 has been associated with carcinogenesis and chemoradioresistance in cervical cancer." (PMID 25148247, 2014).
leiomyoma (1 paper, 2013). A well-circumscribed benign smooth muscle neoplasm characterized by the presence of spindle cells with cigar-shaped nuclei, interlacing fascicles, and a whorled pattern. "Connecting with the PARP1 hub in leiomyoma from older black women were other genes involved in transcription or DNA repair including PRKDC, catenin (cadherin-associated protein), beta 1subunits, MED4, MED19 and MEDIATOR complex." (PMID 23785396, 2013). "For example, MED12 down-regulation was identified in the comparison of tumors and normal tissue, while the Mediator complex and subunits MED4 and MED19 were specifically identified in the IPA analysis of the older black/older white comparisons of leiomyoma." (PMID 23785396, 2013).
melanoma (1 paper, 2019). A malignant, usually aggressive tumor composed of atypical, neoplastic melanocytes. "In melanoma, MED1 and MED14 was increased, while MED4 was reduced." (PMID 31695025, 2019).
tumor (4 papers, 2014 to 2024). "MED3 is derived from a classical Group 3 tumour, MED4, and MED4R result from Group 3 tumours with MYCN gain." (PMID 24887326, 2014). "Our results on a series of germline, tumor DNAs and RNAs did not support any involvement of MED4 in the low penetrance phenotype, but confirmed the differentially methylated status of RB1 CpG85." (PMID 26925970, 2016). "MED4, MED4R and MED5R demonstrated intermediate ABCB1 expression whereas MED3 cells expressed negligible mRNA and protein, again correlating with protein expression levels in primary tumours." (PMID 24887326, 2014). "In general, TCGA RNA-seq data showed that expression of MED1, MED4, and MED14 are not lost in tumors, but varies considerably between tumor specimens compared normal." (PMID 31695025, 2019).
cancer (3 papers, 2009 to 2019). A tumor composed of atypical neoplastic, often pleomorphic cells that invade other tissues. "Loss of the transcriptional activators MED4 may impair transcription of genes with anti-cancer effect, like the vitamin D receptor." (PMID 19911042, 2009). "An important implication of our results is that reduced levels of MED1, MED4, or MED14 may support specific cancer-associated alterations (e.g., SSX2 expression)." (PMID 31695025, 2019).
infection (2 papers, 2022 to 2023). The state of being infected such as from the introduction of a foreign agent such as serum, vaccine, antigenic substance or organism. "MED4, in which RNase E levels were found to increase during lytic infection by the cyanophage P‐SSP7; the increase in RNase E levels may support phage replication by generating a source of nucleotides from stimulated RNA degradation." (PMID 38818332, 2023).
MED4 also shares sentences with these, for which no sentence is quoted: colon cancer (1 paper); dyslipidemia (1).